RASGRP2 (RAS guanyl releasing protein 2)
Description:
Functions as a calcium- and DAG-regulated nucleotide exchange factor specifically activating Rap through the exchange of bound GDP for GTP. May also activate other GTPases such as RRAS, RRAS2, NRAS, KRAS but not HRAS. Functions in aggregation of platelets and adhesion of T-lymphocytes and neutrophils probably through inside-out integrin activation. May function in the muscarinic acetylcholine receptor M1/CHRM1 signaling pathway.
Synonyms: CalDAG-GEFI; CDC25L
Tractability: Antibody: UniProt places it where antibodies can reach, with high confidence; its Gene Ontology location is reachable by antibodies, with high confidence; the Human Protein Atlas places it where antibodies can reach. PROTAC: ubiquitination databases record sites on it; its protein half-life has been measured.
Gene: Protein-coding gene on chromosome 11 (64,726,905 to 64,745,456, reverse strand). Ensembl gene ENSG00000068831.
Subcellular location: Cytoplasm, cytosol; Cell membrane; Synapse, synaptosome; Cell projection, ruffle membrane
Subcellular location (Human Protein Atlas): Plasma membrane
Pathways (Reactome):
Immune System: FCERI mediated NF-kB activation; Rap1 signalling
Hemostasis: Effects of PIP2 hydrolysis
Signal Transduction: Integrin signaling
Gene Ontology:
Molecular function: guanyl-nucleotide exchange factor activity; calcium ion binding; diacylglycerol binding; lipid binding; GTPase regulator activity
Biological process: cellular response to calcium ion; positive regulation of GTPase activity; Ras protein signal transduction; regulation of cell growth; signal transduction; small GTPase-mediated signal transduction
Cellular component: cytosol; plasma membrane; ruffle membrane; synapse
Genetic constraint (gnomAD): Loss-of-function variants: 44 observed, 66.26 expected, observed/expected ratio (o/e) 0.66, 90% interval 0.52 to 0.85. The upper end of that interval is the gene's LOEUF score, 0.85, which puts it in group 3 of 6, group 1 being the genes least tolerant of losing a copy. Missense variants: 663 observed, 805.06 expected, observed/expected ratio (o/e) 0.82, 90% interval 0.77 to 0.88. Synonymous variants: 350 observed, 330.33 expected, observed/expected ratio (o/e) 1.06, 90% interval 0.97 to 1.16.
Gene-disease validity (ClinGen):
ClinGen rates the evidence that RASGRP2 causes each of these diseases.
platelet-type bleeding disorder 18 (autosomal recessive): Definitive. Bleeding disorder due to CalDAG-GEFI deficiency is a rare hematologic disease due to defective platelet function and characterized by mucocutaneous bleeding starting in infancy (around 18 months of age), presenting with prolonged and severe epistaxis, hematomas and bleeding after tooth extraction.
Homologues: Orthologues: macaque RASGRP2 (99% identical), chimpanzee RASGRP2 (99% identical), guinea pig RASGRP2 (98% identical), rat Rasgrp2 (96% identical), mouse Rasgrp2 (96% identical), dog RASGRP2 (96% identical), pig RASGRP2 (94% identical), tropical clawed frog rasgrp2 (63% identical), zebrafish rasgrp2 (56% identical), zebrafish RASGRP2 (53% identical). Paralogues in human: RASGRP3 (50% identical), RASGRP1 (44% identical), RASGRP4 (42% identical), RAPGEF2 (21% identical), RAPGEF6 (20% identical), RALGPS1 (18% identical), SOS1 (18% identical), SOS2 (18% identical), RALGDS (17% identical), RALGPS2 (17% identical), RGL3 (17% identical), RASGRF1 (16% identical), and 12 more.
Diseases named in the same sentence as RASGRP2 in open-access papers:
RASGRP2 is named in the same sentence as 44 diseases in open-access papers, as found by Europe PMC text mining. Sharing a sentence is not in itself a finding about the gene and the disease. The quoted sentences say what the papers report.
lung adenocarcinoma (5 papers, 2020 to 2023). A carcinoma that arises from the lung and is characterized by the presence of malignant glandular epithelial cells. "RAS guanyl releasing protein 2 (RASGRP2) encodes a brain-enriched nucleotide exchanged factor, and research demonstrated that abnormal expression of RASGRP2 in lung adenocarcinoma correlated with the infiltration level of immune cells." (PMID 37964984, 2023). "Analysis of The Cancer Genome Atlas also revealed the positive correlation between GFI1 and RASGRP2 in lung adenocarcinomas." (PMID 35819844, 2022). "The Kaplan-Meier plotter database was used to explore the relationship between the expression of RASGRP2 and the prognosis of patients with lung adenocarcinoma." (PMID 34157800, 2021). "The distribution of RASGRP2 in lung adenocarcinoma was determined by using the human protein mapping database." (PMID 34157800, 2021). "We found that RASGRP2 was low expressed in lung adenocarcinoma, and its expression level was related to the prognosis of patients." (PMID 34157800, 2021). "However, the correlation between RASGRP2 and immune infiltration and malignant features in lung adenocarcinoma (LUAD) has rarely been mentioned." (PMID 36817422, 2023). "RASGRP2 was abnormally expressed in lung adenocarcinoma and correlated with the infiltration level of immune related cells, which might influence the efficacy of immunotherapy." (PMID 34157800, 2021).
lung carcinoma (3 papers, 2022 to 2025). "FCRLA and CD79A were highly expressed in lung cancer cells, whereas RASGRP2 was expressed at low levels." (PMID 40881693, 2025). "First, we analyzed the expression levels of RASGRP2 in 6 different lung cancer cell lines." (PMID 36817422, 2023).
Arthritis (2 papers, 2014 to 2022). Inflammation of a joint. "Whether RasGRP2 contributes to inflammatory diseases as colitis or arthritis, although expectable, may need investigations in the future." (PMID 25118589, 2014).
atherosclerosis (2 papers, 2020 to 2025). A disease characterized by the build-up of fatty material and calcium deposition in the arterial wall resulting in partial or complete occlusion of the arterial lumen. "However, RasGRP2 is also expressed in leukocytes, thus the exact contribution of platelet- and/or leukocyte-associated RasGRP2-dependent signal in atherosclerosis still remains elusive." (PMID 32041177, 2020). "RASGRP2 is an essential factor contributing to endothelial cell dysfunction protection and is often utilized in atherosclerosis research due to its crucial role in cellular autophagy during oxygen deprivation." (PMID 40136477, 2025).
Bleeding Diathesis (2 papers, 2020). "Whole exome sequencing revealed a novel homozygous nonsense RASGRP2 mutation segregating with the bleeding disorder in the family." (PMID 33376940, 2020). "Interestingly, two recent publications reported the cases of patients suffering bleeding diathesis that carry RASGRP2 variants associated with other mutations in the P2RY12 and FERMT3 genes." (PMID 32041177, 2020).
Bleeding disorder platelet type 18 (2 papers, 2020 to 2025). "Inherited platelet function disorder caused by variants of RASGRP2 represents a new congenital bleeding disorder referred to as platelet-type bleeding disorder-18 (BDPLT18)." (PMID 32041177, 2020). "Mutations in RASGRP2 cause the so-called Bleeding disorder platelet type 18 (BDPLT18; OMIM 615888)." (PMID 41301446, 2025).
chronic lymphocytic leukemia (2 papers, 2020 to 2021). "RasGRP2 has been identified as the proto-oncogene in acute myelogenous leukemia and its expression was found to be increased in trisomy 12-associated chronic lymphocytic where it is thought to contribute to the drug resistance-associated enhanced integrin signaling." (PMID 32041177, 2020). "It has also been reported that calcium-sensitive RASGRP2 could promote chronic lymphocytic leukemia cell metastasis through activation of Rap1." (PMID 34079579, 2021). "Additionally, the RasGRP2/Rap1 axis mediates the chronic lymphocytic leukemia cell adhesion and migration in response to an increase in intracellular Ca2+ levels upon CD38 engagement." (PMID 32041177, 2020).
Huntington disease (2 papers, 2021 to 2022). Huntington disease (HD) is a rare neurodegenerative disorder of the central nervous system characterized by unwanted choreatic movements, behavioral and psychiatric disturbances and dementia. "In contrast, RASGRP2 has been reported to be associated with the striatum of mouse Huntington’s disease models, prostate cancer, fibroblast-like synoviocytes from rheumatoid arthritis synovium, and osteosarcoma." (PMID 34681791, 2021). "Furthermore, RASGRP2 has also been reported to be associated with Huntington’s disease, tumors, and rheumatoid arthritis." (PMID 34681791, 2021).
osteosarcoma (2 papers, 2021 to 2022). A usually aggressive malignant bone-forming mesenchymal neoplasm, predominantly affecting adolescents and young adults. "High expression of STC2 and RASGRP2 were correlated with poor prognosis of osteosarcoma." (PMID 34079579, 2021). "Results showed higher expression levels of RASGRP2 and KCNJ3 in two osteosarcoma cell groups (U20S and 143B) compared to the osteoblast cell group (hFOB)." (PMID 36686667, 2022). "The expression levels of RASGRP2 and KCNJ3 were upregulated in osteosarcoma cells, while the expression of ACTG2 was decreased." (PMID 36686667, 2022).
prostate carcinoma (2 papers, 2018 to 2019). A carcinoma that arises from epithelial cells of the prostate gland. "Specific splice variants of PIK3CD, TSC2, and RASGRP2 are associated with a more aggressive oncogenic phenotype in AA prostate cancer cells, which has been hypothesized as an underlying mechanism for prostate cancer health disparities between AA and EA men." (PMID 30463359, 2018).
bladder cancer (1 paper, 2022). "In the present study, we discovered that clinopodiside A promoted RasGRP2 expression and caused autophagy in the bladder cancer cells, which is in contrast to the reports that RasGRP2 favors cell death." (PMID 36199691, 2022). "In the bladder cancer cells, clinopodiside A caused autophagy, which was mediated by the signaling of BLK and RasGRP2, independently." (PMID 36199691, 2022). "We suspect that RasGRP2 regulated autophagy in the bladder cancer cells via Rap1-lysosomes pathway." (PMID 36199691, 2022). "In conclusion, our results suggest that clinopodiside A inhibits the growth of the bladder cancer cells via BLK- and RasGRP2-mediated autophagy." (PMID 36199691, 2022). "In conclusion, our results suggest that clinopodiside A inhibits the growth of the bladder cancer cells via the induction of autophagy which is mediated by BLK and RasGRP2." (PMID 36199691, 2022).
brain inflammation (1 paper, 2024). "It has been suggested that memory B cells expressing RASGRP2 can initiate and propagate an autoreactive T cell response, leading to CNS migration and causing chronic brain inflammation." (PMID 38433828, 2024).
Glanzmann thrombasthenia (1 paper, 2020). "At this stage, sequencing of the RASGRP2 gene will confirm the diagnosis and definitively exclude a variant form of Glanzmann thrombasthenia." (PMID 32041177, 2020). "Indeed, the deficit in RasGRP2 leads to a loss of function of the αIIbβ3 integrin, as does Glanzmann thrombasthenia." (PMID 32041177, 2020).
Leukocyte adhesion deficiency type III (1 paper, 2020). Leukocyte adhesion deficiency type III (LAD-III) is a form of LAD (see this term) characterized by both severe bacterial infections and a severe bleeding disorder. "Decreased CalDAG-GEF1/Rap1 signaling, as in cases of genetic deletion of RASGRP2 in mice or loss of function mutations in humans, has been suggested as a cause of the rare leukocyte adhesion deficiency type III (LAD-III)." (PMID 32120817, 2020).
Peri-Implantitis (1 paper, 2025). An inflammatory process with loss of supporting bone in the tissues surrounding functioning DENTAL IMPLANTS. "The analysis revealed that in peri-implantitis samples, the Ti-high group presented with significantly higher cellular densities of RASGRP2-positive cells than the Ti-low group." (PMID 40102654, 2025).
platelet type bleeding disorder (1 paper, 2021). "The remaining patient was diagnosed with platelet type bleeding disorder 18 and harbored two novel RASGRP2 variants, c.1479dup (p.Arg494Alafs*54) and c.813+1G>A." (PMID 34066320, 2021).
prostate adenocarcinoma (1 paper, 2020). "For example, RASGRP2 methylation levels significantly inversely correlated with its expression levels in stomach adenocarcinoma (STAD), PAAD, and prostate adenocarcinoma (PRAD) with the absolute correlation coefficient not less than 0.3." (PMID 32774369, 2020).
tumor (9 papers, 2018 to 2025). "For example, the RASGRP2 expression levels were inversely associated with tumor purity in 25 TCGA cancer types/subtypes with the Spearman rank correlation coefficient (cor) not greater than −0.3." (PMID 32774369, 2020). "We found that the phosphorylation levels of S123, S578 and S587 of RASGRP2 in primary tumor tissues of LUAD were significantly reduced." (PMID 36817422, 2023). "Next, we compared the phosphorylation of RASGRP2 between normal and tumor tissues using the CPTAC dataset." (PMID 36817422, 2023). "Tumor-infiltrating immune cells were sorted and sequenced at the single-cell level to analyze differences in RASGRP2." (PMID 36817422, 2023). "We found out that the RASGRP2 expression level was lower in LUAD tissues compared with that in non-tumor tissues by bioinformatics analysis and experimental validation." (PMID 36817422, 2023). "Our results revealed that RASGRP2 was not only a novel biomarker involved in the malignant progression of LUAD but also influenced the tumor immune microenvironment (TIM), which might be useful for future cancer therapy." (PMID 36817422, 2023). "Concomitantly, GFI1 reconfigured the chromatin structure of the RASGRP2 gene and increased its expression, causing Rap1 activation and subsequent sustained ERK activation upon detachment, and this led to ERK signaling dependency in tumor cells." (PMID 35819844, 2022). "The most downregulated genes contained known tumor suppressors (ZNF831, AKNA, NR4A1, ARHGAP9, ZBTB16) and regulators of immune response (NLRC5, WDFY4, RASGRP2, IKZF1)." (PMID 39794830, 2025). "To establish the relationship between RASGRP2 and LUAD, we evaluated RASGRP2 expression levels in LUAD tissues and non-tumor tissues through the data from GEO databases." (PMID 36817422, 2023). "CD36 (p value < 2.22e-16), CPA3 (p value < 2.22e-16), NFATC1 (p value = 9.1e-08), and RASGRP2 (p value < 2.22e-16) were highly expressed and SLC2A3 (p value = 0.0015) was lowly expressed in tumor samples." (PMID 32908876, 2020).
cancer (6 papers, 2017 to 2024). A tumor composed of atypical neoplastic, often pleomorphic cells that invade other tissues. "RasGRP2 knockdown nearly completely blocked GFI1-induced ERK activation in suspended cancer cells and restored anoikis of A549 and H460 cells and the ability of A549 cells to form organized acini in the basement membrane." (PMID 35819844, 2022). "For example, the methylation levels of RASGRP2 promoter were significantly higher in 18 TCGA cancer types than in their normal tissues." (PMID 32774369, 2020). "For example, the RASGRP2 expression levels positively correlated with the enrichment levels of CD8+ T cells in 14 TCGA cancer types/subtypes and with the enrichment levels of dendritic cells in 26 TCGA cancer types/subtypes (cor ≥0.3)." (PMID 32774369, 2020). "Thus, GFI1 activated the ERK pathway through RasGRP2 upregulation and consequently conferred cancer cells with anchorage independence." (PMID 35819844, 2022). "For example, RASGRP2 was downregulated in 20 TCGA cancer types." (PMID 32774369, 2020). "However, GFI1-induced substrate detachment escapes anoikis because GFI1 concomitantly upregulates RasGRP2, which in turn activates Rap1 and its downstream ERK signaling pathway to ensure survival of detached cancer cells." (PMID 35819844, 2022).
adenocarcinoma (1 paper, 2009). A common cancer characterized by the presence of malignant glandular cells. "In adenocarcinoma RasGRP2 is −9.3-fold down-regulated and a similar −9.9-fold down-regulation was determined in a comparison with non-transgenic cells." (PMID 19812696, 2009).
nervous system diseases (1 paper, 2021). "The mRNAs of Rgs9, Gpr88, Drd2, Sh3rf2, Tac1, Serpina 9, Rxrg, Drd1, Rasgrp2, Six3, Gpr6, Pdyn, Gng7, and Pde1b were all upregulated (p < 0.05); all of these have been reported to be more or less related to nervous system diseases." (PMID 33819195, 2021).
RASGRP2 also shares sentences with these, for which no sentence is quoted: butyrylcholinesterase deficiency (1 paper); Chediak-Higashi syndrome (1); cholangiocarcinoma (1); cognitive decline (1); colitis (1); colon adenocarcinoma (1); diabetes (1); Ehlers-Danlos syndrome (1); endocervical carcinoma (1); head and neck squamous cell carcinoma (1); immune disorder (1); infection (1); lymphoma (1); migraine (1); pancreatic adenocarcinoma (1); Parkinson ́s disease (1); pontocerebellar hypoplasia (1); rectal cancer (1); rheumatoid arthritis (1); sarcoma (1); skin cutaneous melanoma (1); spastic paraplegia type 7 (1); thymoma (1).